CNBP (CCHC-type zinc finger nucleic acid binding protein)
Description:
Single-stranded DNA-binding protein that preferentially binds to the sterol regulatory element (SRE) sequence 5'-GTGCGGTG-3', and thereby mediates transcriptional repression. Has a role as transactivator of the Myc promoter (By similarity). Binds single-stranded RNA in a sequence-specific manner (By similarity). [Isoform 1]: Binds G-rich elements in target mRNA coding sequences. Prevents G-quadruplex structure formation in vitro, suggesting a role in supporting translation by resolving stable structures on mRNAs. [Isoform 2]: Binds to RNA. [Isoform 4]: Binds to RNA. [Isoform 5]: Binds to RNA. [Isoform 6]: Binds to RNA. [Isoform 8]: Binds to RNA.
Synonyms: RNF163; ZNF9; ZCCHC22; CNBP1; DM2; PROMM
Tractability: PROTAC: ubiquitination databases record sites on it; its protein half-life has been measured.
Gene: Protein-coding gene on chromosome 3 (129,167,818 to 129,184,008, reverse strand). Ensembl gene ENSG00000169714.
Subcellular location: Nucleus; Cytoplasm; Endoplasmic reticulum; Cytoplasm (Isoform 1); Cytoplasm (Isoform 2); Cytoplasm (Isoform 4); Cytoplasm (Isoform 5); Cytoplasm (Isoform 6); Cytoplasm (Isoform 8)
Subcellular location (Human Protein Atlas): Nucleoplasm; Cytosol
Pathways (Reactome):
Disease: SARS-CoV-2 activates/modulates innate and adaptive immune responses
Gene Ontology:
Molecular function: G-quadruplex DNA binding; protein binding; RNA binding; mRNA binding; single-stranded RNA binding; translation regulator activity; nucleic acid binding; zinc ion binding
Biological process: G-quadruplex DNA formation; negative regulation of transcription by RNA polymerase II; cholesterol homeostasis; positive regulation of cell population proliferation; positive regulation of cytoplasmic translation; positive regulation of DNA-templated transcription; positive regulation of transcription by RNA polymerase II; regulation of DNA-templated transcription
Cellular component: cytoplasm; cytosol; endoplasmic reticulum; nucleus
Genetic constraint (gnomAD): Loss-of-function variants: 6 observed, 21.88 expected, observed/expected ratio (o/e) 0.27, 90% interval 0.15 to 0.54. The upper end of that interval is the gene's LOEUF score, 0.54, which puts it in group 2 of 6, group 1 being the genes least tolerant of losing a copy. Missense variants: 111 observed, 244.99 expected, observed/expected ratio (o/e) 0.45, 90% interval 0.39 to 0.53. Synonymous variants: 61 observed, 76.8 expected, observed/expected ratio (o/e) 0.79, 90% interval 0.64 to 0.98.
Cancer hallmarks: escaping programmed cell death (suppresses); invasion and metastasis (suppresses)
Homologues: Orthologues: dog CNBP (100% identical), guinea pig CNBP (100% identical), macaque CNBP (100% identical), mouse Cnbp (100% identical), rabbit CNBP (100% identical), chimpanzee CNBP (97% identical), rat Cnbp (97% identical), pig CNBP (94% identical), zebrafish cnbpb (70% identical), zebrafish cnbpa (68% identical), Drosophila melanogaster CNBP (38% identical), Caenorhabditis elegans K08D12.3 (31% identical). Paralogues in human: ZCCHC13 (57% identical), ZCCHC7 (28% identical), ZCCHC9 (21% identical).
Diseases named in the same sentence as CNBP in open-access papers:
CNBP is named in the same sentence as 102 diseases in open-access papers, as found by Europe PMC text mining. Sharing a sentence is not in itself a finding about the gene and the disease. The quoted sentences say what the papers report.
myotonic dystrophy type 2 (65 papers, 2010 to 2026). Myotonic dystrophy type 2 (MD2), also known as proximal myotonic myopathy, is a very rare genetic multi-system disorder of late childhood or adult-onset characterized by mild myotonia, muscle weakness, and rarely cardiac conduction disorders. "In 1999, the International Myotonic Dystrophy Consortium named Myotonic Dystrophy type 2 all the clinical cases linked to CNBP tetranucleotide expansion." (PMID 39643839, 2025). "It has been known that CCTG repeat expansion in CNBP causes myotonic dystrophy type 2 (DM2), which is a complex disorder characterized by myotonia and muscle dysfunction." (PMID 39894221, 2025). "Myotonic dystrophy type 2 (DM2) is a genetic disease caused by expanded CCTG DNA repeats in the first intron of CNBP." (PMID 37950892, 2024). "Myotonic dystrophy type 2 (DM2) is caused by CCTG repeat expansions in the CNBP gene, comprising 75 to >11,000 units and featuring extensive mosaicism, making it challenging to sequence fully expanded alleles." (PMID 36018009, 2022). "Myotonic dystrophy type 2 (DM2) is a multisystemic disorder caused by a (CCTG)n in intron 1 of the CNBP gene." (PMID 34234810, 2021). "Myotonic dystrophy type 2 (DM2) is caused by expansion of a (CCTG)n repeat in the cellular retroviral nucleic acid-binding protein (CNBP) gene." (PMID 34501382, 2021). "Microsatellite expansions of CCTG repeats in the cellular nucleic acid-binding protein (CNBP) gene leads to accumulation of toxic RNA and have been associated with myotonic dystrophy type 2 (DM2)." (PMID 34517941, 2021). "Myotonic dystrophy type 2 (DM2) is caused by an unstable (CCTG)n expansion in intron 1 of the CNBP gene, leading to a progressive multisystemic disease with muscle, heart and central nervous dysfunctions." (PMID 30100878, 2018). "DM2 (also referred to as proximal myotonic myopathy) is caused by the expansion of the tetranucleotide CCTG-repeat in the first intron of CNBP (cellular nucleic acid-binding protein), formerly known as zinc finger protein 9 (ZNF9) gene." (PMID 29770119, 2018). "CNBP is a nucleic acid chaperone implicated in vertebrate craniofacial development, as well as in myotonic dystrophy type 2 (DM2) and sporadic inclusion body myositis (sIBM) human muscle diseases." (PMID 23667590, 2013). "A CCTG repeat expansion in the CNBP first intron causes the autosomal dominant disease myotonic dystrophy type 2 (DM2)." (PMID 23285195, 2012). "Myotonic dystrophy type 1 results from a trinucleotide CTG repeat expansion in the DMPK gene, encoding serine-threonine kinase, while myotonic dystrophy type 2 results from tetranucleotide CCTG repeat expansion in the CNBP (formerly ZNF9) gene, encoding nucleic acid-binding protein." (PMID 40869293, 2025). "Muscleblind‐like 1 protein no longer binds to CCUG repeat‐expanded cellular nucleic acid‐binding protein (CNBP) RNA connected to type 2 myotonic dystrophy (DM2) pathogenicity as a result of modification of the enlarged intronic CCUG repeats in CNBP, whose expression is linked to DM2 in humans." (PMID 39691424, 2024). "Myotonic dystrophy type 2 (DM2) is caused by an unstable tetranucleotide (CCTG) repeat expansion in the CCHC-type zinc finger nucleic acid binding protein (CNBP) gene." (PMID 31681146, 2019). "Myotonic dystrophy type 2 (DM2) is caused by a CCTG repeat expansion in intron 1 of the CNBP gene located on chromosome 3q211,2." (PMID 30038349, 2018). "A related disease, Myotonic Dystrophy, type 2 (DM2), also presents with cataracts and is caused by repeat expansion in the CNBP gene, which encodes a nucleic acid (including RNA) binding protein." (PMID 41542625, 2026). "Myotonic dystrophy type 2 (DM2) is an autosomal dominant, multisystemic disorder caused by the expansion of CCTG repeats in the first intron of the CNBP gene." (PMID 42003432, 2026). "Initial studies on CNBP mainly focused on its role in the embryogenesis of craniofacial structures and the human disease myotonic dystrophy type 2." (PMID 38626179, 2024).
myotonic dystrophy type 2 (continued). "Myotonic dystrophy type 2 is characterized by large CCUG repeats in the CNBP gene that result in myopathy." (PMID 38378748, 2024). "Pathological RNA foci and MBNL sequestration are also observed in the type 2 myotonic dystrophy (DM2), which is caused by the expansion of the CCTG repeats in intron 1 of the CNBP/ZNF9 gene." (PMID 38153590, 2024). "Myotonic dystrophy type 2 (DM2; Proximal myotonic myopathy, MIM#602668) is caused by a CCTG repeat expansion in the first intron of the CNBP gene (MIM#115995)." (PMID 36555146, 2022). "Myotonic dystrophy type 2 (DM2; MIM#602668) is an autosomal dominant multisystemic disorder caused by a (CCTG)n repeat expansion in intron 1 of CNBP gene (previously ZNF9) on chromosome 3q21.3." (PMID 34234810, 2021). "Myotonic dystrophy 2 (DM2; also known as proximal myotonic myopathy; OMIM 602668) is caused by a heterozygous expansion of 75 or more CCTG repeats in intron 1 of CNBP." (PMID 34564083, 2021). "For comparison, we also examined the similarly slowly progressing myotonic dystrophy type 2 (DM2), caused by expansion of a tetranucleotide repeat (CCTG*CAGG)n in intron 1 of CNBP (ZNF9) and in overlapping antisense genes." (PMID 32744322, 2020). "The cause of myotonic dystrophy type 1, known as Steinert disease, are alterations to DMPK, while myotonic dystrophy type 2 results from defects in CNBP (also known as ZNF9)." (PMID 32580419, 2020). "Partial retention of expanded CCTG repeat-containing first intron of the CCHC-type zinc finger (CNBP, formerly known as ZNF9) gene has also been reported in myotonic dystrophy type 2 (DM2)." (PMID 26916632, 2016). "Similarly, as discussed, testing for OPMD (PABPN1, R75) and myotonic dystrophy type 2 (CNBP (ZNF9), R410) are only available through PCR-based tests and need to be requested additionally to the panels of interest." (PMID 39349043, 2025). "RNA-dependent pathophysiological mechanisms and RAN translation of tetrapeptides (polyLPAC and polyQAGR) also coexist in myotonic dystrophy type 2 (DM2, MIM #602668), caused by CCTG/CAGG repeat expansions in CNBP (CCHC-type zinc finger nucleic acid-binding protein, MIM #116955)." (PMID 38835438, 2021). "A pathomechanism similar to that observed in DM1 was also proposed for myotonic dystrophy type 2 (dystrophia myotonica 2, DM2, OMIM: 602668), a disease caused by an expansion of CCTG repeats in the first intron of the CCHC-type zinc finger nucleic acid binding protein gene." (PMID 31428124, 2019). "Myotonic dystrophy type 2 (DM2), which presents symptoms similar to those of DM1, is caused by an abnormal expansion of CCTG repeat sequences within intron 1 of the CNBP gene." (PMID 40565550, 2025). "CNBP is also involved in muscle human diseases, such as myotonic dystrophy type 2 (DM2, proximal myotonic myopathy, OMIM # 602668) and the age-related sporadic inclusion body myositis (sIBM)." (PMID 23667590, 2013). "Cellular nucleic acid‐binding protein (CNBP) is a conserved protein of 19 kDa,3 while amplification of its CCTG repeat within intron 1 leads to myotonic dystrophy type 2, an autosomal dominant multisystem disease." (PMID 37186134, 2023). "Myotonic dystrophy type 2 (DM2) is a genetic, autosomal dominant disease due to expansion of tetraplet (CCTG) repetitions in the first intron of the ZNF9/CNBP gene." (PMID 24722564, 2014). "The disorder encompasses two genetically distinct types: myotonic dystrophy type 1 (DM1, OMIM 160900) and myotonic dystrophy type 2 (DM2, OMIM 602668), attributable to CTG expansion in 3’UTR of the DMPK gene and CCTG repeats in the first intron of the CNBP gene, respectively." (PMID 40133672, 2025). "One of these disorders, myotonic dystrophy type 2 (DM2; OMIM_#602668), is connected to expansion of a (CCTG)n repeat tract located in the first intron of the cellular retroviral nucleic acid-binding protein (CNBP; also called zinc finger protein 9, ZNF9) gene." (PMID 34501382, 2021).
myotonic dystrophy type 2 (continued). "Myotonic dystrophy type 2 (DM2, OMIM 602688) results from an unstable tetranucleotide CCTG repeat expansion in intron 1 of the nucleic acid-binding protein (CNBP) gene (previously known as zinc finger 9 gene, ZNF9; OMIM 116955) on chromosome 3q21." (PMID 30100878, 2018).
myotonic dystrophy (28 papers, 2007 to 2026). An inherited progressive disorder affecting the muscles. "Non-dystrophic myotonias (NDMs) are skeletal muscle disorders involving myotonia distinct from myotonic dystrophy caused by a mutation of the DMPK or ZNF9/CNBP gene." (PMID 31189464, 2019). "Myotonic dystrophies (DM) are slowly progressing multisystemic disorders caused by repeat expansions in the DMPK or CNBP genes." (PMID 30140252, 2018). "Additionally, CNBP loss of function might also play a role, as Cnbp‐deficient mice develop key features of myotonic dystrophy." (PMID 31721251, 2020). "CNBP is dysregulated in iPSC derived from patients with myotonic dystrophy, whereas SOX4 and DPPA4 are transcription factors shown to be dynamically regulated during endoderm induction from iPSCs." (PMID 36631981, 2023). "Second, both DM1 and DM2 are classified as myotonic dystrophies but DM1 is caused by DMPK CTGexp and DM2 by CNBP CCTGexp, mutations and these two genes are located on different chromosomes and encode proteins with very different functions." (PMID 31323950, 2019). "For instance, DM2 is caused by up to 11,000 CCTG repeats in CNBP intron 1 but this disease is generally recognized as a less severe type of myotonic dystrophy distinguished by relatively late-onset and lack of a congenital form." (PMID 31323950, 2019). "Additional studies revealed the unstable tetranucleotide CCTG repeat expansion in intron 1 of CNBP (Cellular Nucleic Acid-Binding Protein) gene, located on the long arm of chromosome 3 (chr 3q21.3) (OMIM #116955), as the causative mutation for these “Steinert-Like” myotonic dystrophy." (PMID 39643839, 2025). "Myotonic dystrophy (MD) is a muscular dystrophy characterized by progressive muscle loss and weakness, caused by a genetic mutation of the Dystrophy myotonic protein kinase (DMPK) or the CCHC-type zinc finger nucleic acid binding protein (CNBP) genes (MD1 and MD2, respectively)." (PMID 37404739, 2023). "Myotonic dystrophy (DM) is a multi-systemic, progressive disease caused by expanded CTG or CCTG repeats in the 3′ UTR of the dystrophia myotonic protein kinase (DMPK) gene (DM type 1 [DM1]) or the first intron of the cellular nucleic acid binding protein (CNBP) gene (DM type 2 [DM2]), respectively." (PMID 33472074, 2021).
myotonic dystrophy type 1 (27 papers, 2010 to 2025). Steinert disease, also known as myotonic dystrophy type 1, is a muscle disease characterized by myotonia and by multiorgan damage that combines various degrees of muscle weakness, arrhythmia and/or cardiac conduction disorders, cataract, endocrine damage, sleep disorders and baldness. "In humans, expansion of a CCTG repeat in intron 1 of CNBP/ZNF9 causes myotonic dystrophy 1, a common type of muscular dystrophy." (PMID 30235899, 2018). "Clinically, two subtypes are recognized: DM type 1 (Steinert’s disease), caused by a trinucleotide repeat expansion in the DMPK gene, and DM type 2, caused by a tetranucleotide repeat expansion in the ZNF9/CNBP gene." (PMID 32471196, 2020). "Myotonic dystrophies types 1 (DM1) and 2 (DM2) are autosomal dominant, multisystemic diseases, due to CTG- or CCTG-repeat expansion mutations in DMPK and CNBP, respectively." (PMID 32373059, 2020). "Myotonic dystrophy 1 and 2 (DM1, DM2) are caused by unstable CTG or CCTG repeats within the gene DMPK or CNBP (ZNF9), respectively." (PMID 29910736, 2018). "Indeed, hypercholesterolemia and elevated TG have also been reported in LGMD type 1C (caveolin-3 mutations) and myotonic dystrophies types 1 and 2 (DMPK and CNBP mutations, respectively) — although often in the absence of control conditions or using experimental approaches." (PMID 36447272, 2022). "This is a dominant inherited, multi-systemic, disease due to the expansion of the CTG triplet repeat in the DMPK gene for type 1 myotonic dystrophy (DM1) and the CCTG-tetranucleotide sequence in the CNBP gene for the DM2." (PMID 38678519, 2024). "In myotonic dystrophy type 1 and 2 (DM1 and DM2), for example, mutations in the DMPK and ZNF9/CNBP genes, respectively, disrupt the alternative splicing of the CLCN1 gene, creating a secondary reduction in sarcolemmal ClC-1 protein expression and current density." (PMID 32117034, 2020).
gastric cancer (18 papers, 2019 to 2026). A primary or metastatic malignant neoplasm involving the stomach. "Gain- and loss-of-function studies show that CNBP facilitates HuR expression, growth, and aggressiveness of cancer cells, suggesting the oncogenic roles of CNBP in gastric cancer progression." (PMID 31718709, 2019). "In a cohort of 81 gastric cancer cases, lower circ-HuR expression (P = 3.0 × 10− 3) and higher expression of CNBP (P = 7.0 × 10− 4) or HuR (P = 3.5 × 10− 2) was associated with lower survival probability of patients." (PMID 31718709, 2019). "In the current study, mining of public gastric cancer datasets reveals that higher expression of CNBP is associated with poor outcome of patients." (PMID 31718709, 2019). "As a nuclear down-regulated noncoding RNA, circHuR suppresses HuR expression and gastric cancer progression by inactivating CNBP." (PMID 38635778, 2024). "For example, circHuR interacts with CCHC-type zinc finger nucleic acid-binding protein (CNBP) and blocks its binding to the HuR promoter, leading to reduced HuR expression to further inhibit gastric cancer progression." (PMID 37124518, 2023). "Circ-HuR interacts with CNBP protein to restrain its binding to HuR promoter in gastric cancer cells." (PMID 36800233, 2023). "The lncRNA SUMO1P3 enhances proliferation, invasiveness, and drug resistance in gastric cancer cell lines by directly binding to CNBP, resulting in high levels of c-myc and cyclinD1 (CCND1)." (PMID 35991559, 2022). "Circ-HuR serves as a tumor suppressor to inhibit CNBP-facilitated HuR expression and gastric cancer progression, indicating a potential therapeutic target for gastric cancer." (PMID 31718709, 2019). "We further investigated the interplay effects between circ-HuR and CNBP in regulating HuR expression and gastric cancer progression." (PMID 31718709, 2019). "Meanwhile, circ-HuR restrains the transcription of HuR by inhibiting CNBP transactivation, and suppresses the growth and aggressiveness of gastric cancer in vitro and in vivo." (PMID 31718709, 2019). "Collectively, these results indicated that circ-HuR suppressed gastric cancer progression by inhibiting CNBP transactivation in vivo." (PMID 31718709, 2019). "CircHuR inhibits gastric cancer progression via inhibiting CNBP-facilitated HuR expression." (PMID 38635778, 2024). "For example, circRNA human antigen R (circHuR) interacted with CCHC‐type zinc finger nucleic acid binding (CNBP) to inhibit the binding of CNBP to the HuR promoter, thereby downregulating HuR expression levels and inhibiting the pathological process of gastric cancer." (PMID 37864389, 2024). "Interestingly, CNBP promotes the expression of HuR at transcription level via binding to HuR promoter in gastric cancer cells." (PMID 31718709, 2019). "Cox regression analysis revealed that distant metastasis [hazard ratio (HR) = 2.809, P = 0.002], tumor-node-metastasis (TNM) stage (HR = 2.519, P = 0.015), circ-HuR levels (HR = 0.616, P = 0.012), and CNBP expression (HR = 2.643, P = 0.003) were prognostic factors for gastric cancer patients." (PMID 31718709, 2019). "In addition, the circ-HuR (R = -0.602, P < 1.0 × 10− 4) or CNBP (R = 0.683, P < 1.0 × 10− 4) levels were negatively and positively correlated with those of HuR in these gastric cancer tissues, respectively." (PMID 31718709, 2019). "Furthermore, circ-HuR can bind CCHC-type zinc finger nucleic acid binding protein (CNBP), inhibit CNBP-promoted human antigen R (HuR) expression and the development of gastric cancer, and may become a potential therapeutic target for gastric cancer." (PMID 32300345, 2020). "circHuR interacts with CCHC-type zinc finger nucleic acid binding protein (CNBP) and inhibits CNBP binding to HuR promoter, thereby suppressing gastric cancer progression by inhibiting CNBP transactivation." (PMID 35768865, 2022).